TNF (tumor necrosis factor)
Diseases named in the same sentence as TNF in open-access papers (continued):
Sharing a sentence is not in itself a finding about the gene and the disease.
tumor (continued). "Furthermore, proinflammatory cytokines including CXCL9, TNF-α, CCL4, and CCL3 were also upregulated in the tumor following the combined therapy, further demonstrating the change in the immune environment." (PMID 38705987, 2024). "Correlation analysis showed that B. thetaiotaomicron abundance positively correlated the RNA level of CD8A, GZMB, IFN-gamma and TNF, which represented the function of cytotoxic CD8+ T cells, which is essential immune cells for Immune surveillance of tumor cells." (PMID 38270111, 2024). "Analysis of the tumor‐infiltrating lymphocytes (TILs) in CPT‐treated tumors showed the augmented function of CD8+ T cells, as indicated by the increased expression of interferon‐γ (IFN‐γ) and TNF‐α in CD8+ T cells." (PMID 38189627, 2024). "In addition, MCs produce a number of different mediators such as IL-6, IL-8, CCL25, CXCL10, CXCL, and TNF-α, which are engaged in TME remodeling and promote tumor development, metastasis, and neovascularization." (PMID 39776907, 2024). "Moreover, TLR signaling can promote M1 polarization, which can mediate tumor destruction via the secretion of proinflammatory factors, such as NFκB, IFN-γ, and TNFα, that directly inhibit cancer cell growth." (PMID 38201300, 2024). "In accordance with the literature, not only are all leukocytes capable of producing TNF, but different tumor cells, including CML cells, also produce it, leading to increased systemic levels of TNF that are typically observed in patients with chronic myeloid leukemia." (PMID 38337668, 2024). "In addition, higher expressions of IL‐6, TNF‐α, and IFN‐γ were expressed in lung metastatic nodes of the RBC‐PEI‐AD11 group compared with other groups to promote anti‐tumor immune response." (PMID 37997186, 2024). "It was also found that blocking TIGIT signaling pathway of malignant tumors could significantly increase the expression of IFN-γ and TNF-α in tumor-specific CD8+ T cells and significantly improve the anti-tumor immune response." (PMID 38534423, 2024). "Conversely, treating tumor-bearing mice with IL-4 complexes (IL-4 bound to anti-IL-4 mAb to enhance its in vivo half-life) recapitulated the effect of anti-PD-1 mAb on OT-I CD8+ T cell expansion and TNF-α+IFN-γ+ double-producer T cells." (PMID 38417020, 2024). "The DMPtNPS@cGAMP + RT group exhibited a significant increase in anti‐tumor cytokines, namely IFN‐γ, IFN‐α, IFN‐β, TNF‐α, and IL‐2, and a more pronounced decrease in pro‐tumor cytokines, including IL‐1β, IL‐10, IL‐4, and TGF‐β, as measured by ELISA kits, in comparison to the other treatment groups." (PMID 38063844, 2024). "The immune system recognizes cytokines released by dead tumor cells (high mobility group protein B1 (HMGB1), heat shock proteins (HSPs), S100, oxidized DNA, ATP, etc.) and further presents them to CTL, releasing TNF, including TNF- α And IFN- γ." (PMID 38339426, 2024). "While TNF-α promotes inflammation and may exacerbate disease progression, TGF-β’s role appears to be more context-dependent, potentially exhibiting tumor-suppressive effects that are overridden in the leukemic microenvironment." (PMID 39658797, 2024). "Immunohistochemistry (IHC) and flow cytometric analysis indicated that the numbers of tumor-infiltrating and splenic CD8+, Granzyme B+CD8+ and TNF-α + CD8+ T cells were higher in mice treated with APG-2575 + PD-1 blockade than in those treated with any single drug alone." (PMID 38062129, 2024). "We observed that GSDME could increase the infiltrations of CD8+T cells and their functions secreting more IL2, TNFα, GZMB, and PFN against tumor in human samples." (PMID 38853246, 2024). "It is crucial to note that therapy-induced tumor cell death promotes the production of growth factors and cytokines, including WNT, EGF, TNF, IL-17, and IL-6, by cells in the TME to promote the survival of remaining tumor cells and play a role in fostering therapy resistance." (PMID 38799159, 2024).
tumor (continued). "Furthermore, cytokines such as IL-6, IL-21, IL-17A, and tumor necrosis factor-α (TNF-α) induce tumor-supportive microenvironment, while interferon-γ (IFN-γ) exerts tumor-suppressive response." (PMID 38741166, 2024). "A study done by administering combined cisplatin and Akkermansia muciniphila in LC mice group resulted in small tumor volume, decreased Treg ratio, reduced Fas ligand protein expression level, and upregulated antitumor IFN‐γ, IL‐6, and TNFα compared with cisplatin only administered mice group." (PMID 39584048, 2024). "Moreover, although NK and CD8+ T cells recruited to liver tumours of wild-type mice produce IFNγ and TNF, the production of IFNγ and TNF was reduced in the remaining NK and CD8+ T cells present in the liver of tumour-bearing Clec4fcreId3f/f mice." (PMID 38326607, 2024). "Notably, complete tumor regression and good drug tolerance were observed in 80−100% of treated mice, and significant increases in IFN‐β, IL‐6, and TNF‐α were observed in the tumor and plasma." (PMID 38525112, 2024). "For example, tumor necrosis factor-α (TNF-α), a proinflammatory cytokine predominantly produced by macrophages, contributes to EMT induction in tumor cells and invasion through the activation of the nuclear factor kappa-B (NF-κB) and protein kinase B (AKT) signaling pathways." (PMID 39118068, 2024). "In addition, SPP1 + Mac-derived TNF-α and IL-1β promoted the expression of OPN in both tumor cells and macrophages." (PMID 39726047, 2024). "Extracellular HMGB1 can induce M1-like polarization of TAMs in the tumor microenvironment of glioblastoma, activating the ERK1/2/NF-κB/NLRP3 inflammatory pathway and promoting the release of various cytokines (e.g., IFN-γ, IL-6, TNF-α, and IL-8)." (PMID 37897664, 2024). "IL‐17A and TNF synergistically induced the Th17‐promoting cytokines IL‐6 and IL‐1β as well as the Th17‐attracting chemokine CCL20 in mesothelial cells, indicating a reciprocal crosstalk that potentiates the tumor‐promoting role of Th17 cells in OC." (PMID 38566518, 2024). "Both TNF-α and IFN-γ are secreted by activated T cells and induce PD-L1 expression in tumor tissues, which might serve as a reservoir of bsPD-L1." (PMID 38774209, 2024). "Additionally, a study on a rat tumor model that received radicicin-based PDT along with interleukin-12 delivered by adenovirus (AdmIL-12) showed significant boosts in interferon and TNF production as well as CD8+ T cell proliferation." (PMID 38646546, 2024). "PD-L1, generated by tumor cells, restricts the immune response of the host by binding to PD-1 on the surface of T cells, which inhibits the release of cytokines including interleukin 2 (IL2), tumor necrosis factor alpha (TNFα), and interferon gamma (IFN γ)." (PMID 38893691, 2024). "GSEA showed that mT4 macrophages were enriched in TGFβ and TNFα signaling via NF-kB pathways, while B16F10 macrophages were enriched in interferon-gamma and alpha response pathways, indicating their opposing functions in the tumor." (PMID 38987547, 2024). "Specifically, compared with DMSO treatment, UA treatment increased the expression of IFN‐γ, TNF‐α, IL‐2, CD107a, and granzyme B in OT‐I CD8+ CTLs and enhanced the cytotoxic activity against antigen‐pulsed EL4 tumor cells in vitro." (PMID 38447147, 2024). "In addition, the serum and tumor homogenate concentrations of proinflammatory cytokines, including IFN‐γ, TNF‐α, IL‐6 and IL‐1β, increased significantly in the B16F10 cell–rechallenged mice of the HM‐NPs group." (PMID 38353384, 2024). "Tumor cells influence the behavior of surrounding cells by secreting cytokines and chemokines, such as vascular endothelial growth factor (VEGF) and tumor necrosis factor (TNF), and by regulating tumor stromal formation and function." (PMID 39194667, 2024). "Indeed, p65 deficiency enhances CD8+T cells proliferation and increases levels of IFN-γ, TNF-α and IL-1β, which lead to a decreased GBM tumor growth." (PMID 38397187, 2024).
tumor (continued). "With tumor cell stimulation, the CART-19 cells exhibited heightened functional cytokine and chemokine secretion, especially the production of GM-CSF, IFN-γ, IL-2, IL-4, IL-8, IL-12, IL-13, MIP-1α/β, and TNF-α/β." (PMID 38773607, 2024). "However, in advanced tumor models, TANs have been observed to induce CD8 T-cell apoptosis through the TNFα pathway and NO, contributing to an immunosuppressive environment." (PMID 38360737, 2024). "The ambiguity of immuno-stimulatory T-helper (TH) cell type 1 (TH1-type) cytokines, including TNF-α, IFN, IL-2, IL-12, etc., lies in the fact that they can induce cell-mediated immunity and tumor suppression; still, they can also act as pro-inflammatory players." (PMID 38541074, 2024). "Butyrate is primarily known as an energy source for colonocytes and a beneficial metabolite for gut health; however, it also exhibits anti-tumor effects, such as reducing tumor necrosis factor (TNF) levels, which in turn may lead to decreased tumor growth." (PMID 39594997, 2024). "One powerful T-cell effector mechanism that can eliminate antigen-negative tumor cells is TNF-mediated bystander death." (PMID 39068665, 2024). "Similarly, the mRNA-LNPs strongly promoted T-cell-dependent killing and secretion of IFN-λ, TNF-α, and granzyme B against other HER2-positive tumor cells, including NCI-H460, SKOV-3, and MDA-MB-231." (PMID 39066446, 2024). "Treatment with MCP led to an increase in CD86 expression and TNF-α secretion, indicative of enhanced M1 polarization, while reducing CD206 and CD163 expression along with IL-10 secretion, thus supporting a shift towards a more anti-tumor immune response." (PMID 39593969, 2024). "Furthermore, various cytokines secreted by lymphocytes, including interferon-gamma (IFN-γ) and tumor necrosis factor-alpha (TNF-α), contribute to tumor suppression and extend the survival of cancer patients." (PMID 39654896, 2024). "Macrophage‐secreted TNF‐α binds to TNFR on the surface of tumour cells and induces caspase‐8 cleavage of GSDMC, reversing the apoptotic pathway into pyroptosis and contributing to anti‐tumour immunity." (PMID 38652105, 2024). "In addition, Rg3 induces the secretion of TNF-α or TGF-β and promotes IFN-γ production by tumor cells." (PMID 38361933, 2024). "Treatment with the PD-1 antibody alone could reactivate the tumor-infiltrated CD8+ T cells in H22 tumors by increasing the proportions of IFNγ+, TNFα+ and Granzyme B+ (GZMB+) cells within the CD8+ T cell population." (PMID 38684648, 2024). "CD8+ T cells are one of the important cells that participate in adaptive immune response, and they eliminate intracellular infection, control chronic infection, and eliminate tumor by producing cytokines (such as IL-2, IFN-γ, and TNF-α) and cytotoxic molecules (perforin and granzyme)." (PMID 38678017, 2024). "Key cytokines such as TNF, IL-1, IL-6, IL-12, IL-18 (stimulatory), and TGF-β, IL-4, and IL-10 (inhibitory) mediate interactions between these cells, creating a network that facilitates tumor growth and immune evasion." (PMID 39449800, 2024). "CTLs release TNF-α and IFN-γ, further stimulating the anti-tumor immune responses." (PMID 38543305, 2024). "TMQ administration downregulated the tumor necrosis factor-α (TNF-α), interleukin-6 (IL-6), and the glutathione (GSH) level and upregulated interferon-γ (IFN-γ), reactive oxygen species (ROS), and malondialdehyde (MDA) levels in the serum of tumor mice." (PMID 39508039, 2024). "Additionally, the receptors on NK cells can selectively target tumor cells by recognizing growth factors like PDGF, thereby triggering the release of IFN-γ and TNF-α to inhibit tumor growth." (PMID 38533507, 2024). "TANs have pro-tumor activity by producing ARG1, IL-10, TGF-β, and VEGF, and inhibiting cytotoxic T cells by expressing higher levels of immunosuppressive molecules, such as PD-L1, ARG1, and IDO, and lower of anti-tumor molecules, such as ROS and TNF-α." (PMID 39430759, 2024).
tumor (continued). "Compared with the common T cell group, EpCAM-CAR-T cells had strong a cytotoxic impact against EpCAM-positive tumour cells, and EpCAM-CAR-T cells could secrete a large amount of TNF-α and INF-γ." (PMID 39107717, 2024). "TNF-α has been reported to promote inflammation and IBD-CRC, facilitating DNA damage, stimulating angiogenesis and inducing COX-2 expression that also induces angiogenesis, resulting in tumor growth." (PMID 38628384, 2024). "Notably, PEG-MnMOF@PTX demonstrated potent induction of proinflammatory factors TNF-α and IL-6 secretion, along with TGI evidenced by a tumor suppression of up to 84.4% and a substantial improvement in survival." (PMID 38715912, 2024). "CD8+ T cells play a crucial role in anti-tumor immunity and eliminate tumors through several mechanisms such as inducing apoptotic cell death via perforin-granzyme or Fas-FasL interaction and by secreting cytokines such as IFN-ɣ and TNF-α within the TME." (PMID 39682129, 2024). "We also showed that TNF-α and IL-1β upregulate the expression of OPN in tumor cells and macrophages; thus, these factors may be candidate targets through which antitumor efficacy can be enhanced." (PMID 39726047, 2024). "In vivo, feeding breast cancer rats with nano-encapsulated quinoa seed oil inhibited tumor proliferation, activated cell apoptosis, and suppressed the expression of TNF-α, MYC, and PIK3CA, with no hepatorenal toxicity observed." (PMID 39061898, 2024). "Because the literature suggests that TGFβ, TNFα, and hypoxia are common tumor microenvironment factors that drive PMT, we first established their relevance in human tumors using publicly available patient data, beginning with TCGA bulk tumor transcriptomics." (PMID 38337036, 2024). "Within the tumor, markers of immunogenic cell death [calreticulin and high-mobility group box 1 protein (HMGB1)] were increased, and the serum proinflammatory cytokines IL-6, TNFα, and IFNγ also were upregulated, as compared to other treatment groups." (PMID 38803496, 2024). "Given that ICBs immunotherapy promotes the secretion of IFN-γ, TNF-α and other inflammatory cytokines in tumor microenvironment, we first assessed the influence of cytokines IFN-γ and TNF-α on the expression of CD73 in tumor cells." (PMID 39002018, 2024). "On the day of tumor capture, IFN-γ and TNF-α ELISAs were performed on sera from HNSCC mouse models with knockout or overexpression of SPHK1/MMP1, with the results showing that SPHK1/MMP1 expression was negatively correlated with IFN-γ and TNF-α." (PMID 39629135, 2024). "We also analyzed the relative expression of CD8+ T cell activation marker tumor necrosis factor alpha (TNFA) and interferon-gamma (IFNG) in tumor tissue, the average relative expression of TNFA and IFNG in FMD group is 1.45 times and 1.3 times higher than control group." (PMID 38918380, 2024). "Moreover, the NicheNetR analysis revealed the potential ligands expressed by C3–4 of LN tumor cells that drive exhausted signatures of CD8 TDYS in RR TFHL, including IL21, TNF, TGFB1, CD80, and CD86." (PMID 38012392, 2024). "To analyze whether the bsAb mediated T cell activation in response to the tumor cells, we measured the levels of the effector molecules granzyme B, IFN-λ, and TNF-α secreted into the medium by T cells." (PMID 39066446, 2024). "NKs cells are crucial components in the anti-tumor immune response after RFA, which could eradicate the tumor cells directly or induce the apoptosis of tumor cells by secreting IFN-α and TNF-α." (PMID 38348038, 2024). "The upregulation of these molecules facilitates the recruitment of anti-tumor T-cells and triggers an immune response accompanied by the release of pro-inflammatory molecules like IL-1, IL-2, IL-6, IL-8, IL-12, VEGF, EGFR, IFN-α, IFN-ß and TNF-α." (PMID 39518094, 2024).
tumor (continued). "In this regard, the in vitro data suggest that the free bacteria or the infected tumor cells present into the TME are capable to stimulate the activation of macrophages and the release of cytokines and chemokines (TNF-α, IL-6, IL-12, and CXCL10) in a MyD88-dependent manner." (PMID 38835781, 2024). "Notably, cytokines like IL-2, IL-6, TNF-α, and IFN-γ, known for their inflammatory enhancement properties, contribute to stimulating tumor cell immunity, thereby fostering anti-tumor activity." (PMID 39351237, 2024). "Furthermore, examination of tumor‐draining lymph nodes showed an increase in CD8+ T cells in the PS‐treated group, with more CD4+ T cells expressing TNFα." (PMID 38900071, 2024). "Moreover, puerarin decreases the level of pro-tumor cytokines (IL-10, TGF-β, and IL-4) and increases the expression of anti-tumor cytokines (IFN-γ, IL-12, and TNF-α)." (PMID 38361933, 2024). "T cells armored with GzB-IL18 produced significantly more TNF-⍺ than those with pro-IL18 or no armoring when stimulated on tumor cell monolayers or with CD3+CD28 crosslinking." (PMID 38745414, 2024). "Moreover, SPP1 + Mac-derived TNF-α and IL-1β promoted the expression of OPN in both tumor cells and other adjacent macrophages through different signaling pathways." (PMID 39726047, 2024). "Analysis of tumor growth showed that the tumors grew larger from day 4 to day 14, post TPA treatment, in groups of mice treated either with saline or control nontargeted vector, whereas mice receiving the targeted RGD4C.TPA.TNFα had their tumor growth reduced." (PMID 37331004, 2023). "Expansion of TNFα expressing splenic KSLs was also identified in the LLC and 1956 tumor models." (PMID 37134077, 2023). "TNF-α is one of the most abundant pro-inflammatory cytokines followed by CXCL-8 in the oral MSC secretome, which could potentially mediate tumor development." (PMID 38170015, 2023). "Tumor-derived long intergenic non-coding RNA-482 (LINC00482) was shown to increase levels of pro-inflammatory cytokines such as IL-6, tumor necrosis factor alpha (TNFα), and IL-1 beta (IL-1β), as well as VEGF, which led to increased inflammation and angiogenesis." (PMID 37569686, 2023). "In keeping with these findings, the EOAI3402143 treatment alone or combination with anti-CTLA-4 significantly reduced the PD-1 protein abundance in tumor-infiltrating CD3+ T cells and enhanced the production of IFN-γ, TNF, and GzmB in tumor-infiltrating CD8+ T cells compared with control treatment." (PMID 37208329, 2023). "Tumor necrosis factor (TNF)-related apoptosis-inducing ligand (TRAIL) is a member of the TNF superfamily that selectively induces apoptosis in tumor cells without harming normal cells, making it an attractive agent for cancer therapy." (PMID 37345089, 2023). "Results showed that CPG administration of 100 mg/kg could effectively inhibit tumor growth in mice with an inhibitory ratio of 45.37% and significantly improve the expression of Interleukin-2 (IL-2), Interferon-γ (IFN-γ), and Tumor Necrosis Factor-α (TNF-α)." (PMID 37958581, 2023). "Furthermore, PE enhanced the proliferative capacity of anti-tumor T cells (increased expression of Ki67, CD137, GZMB or IFN-γ, TNF-a) and reversed T cell exhaustion (impaired CD95 or PD-1 expression)." (PMID 37355637, 2023). "Splenic CD8+ T cells in tumor-bearing mice treated with the combination of 5AZADC and ADU-S100 expressed higher levels of IFN-γ and TNF-α relative to the mice treated with ADU-S100 alone indicating that combination therapy stimulates a stronger systemic antitumor T cell response." (PMID 36949064, 2023). "It has been extensively studied that Tregs generate a strong pro-inflammatory environment in GI tumors through the secretion of inflammatory cytokines such as IL-12, TGF-β, and TNF-α promoting an immunosuppressive TME and, therefore, supporting tumor invasiveness and metastasis formation." (PMID 37371856, 2023).